MAPK11 (mitogen-activated protein kinase 11)
Description:
Serine/threonine kinase which acts as an essential component of the MAP kinase signal transduction pathway. MAPK11 is one of the four p38 MAPKs which play an important role in the cascades of cellular responses evoked by extracellular stimuli such as pro-inflammatory cytokines or physical stress leading to direct activation of transcription factors. Accordingly, p38 MAPKs phosphorylate a broad range of proteins and it has been estimated that they may have approximately 200 to 300 substrates each. MAPK11 functions are mostly redundant with those of MAPK14. Some of the targets are downstream kinases which are activated through phosphorylation and further phosphorylate additional targets. RPS6KA5/MSK1 and RPS6KA4/MSK2 can directly phosphorylate and activate transcription factors such as CREB1, ATF1, the NF-kappa-B isoform RELA/NFKB3, STAT1 and STAT3, but can also phosphorylate histone H3 and the nucleosomal protein HMGN1. RPS6KA5/MSK1 and RPS6KA4/MSK2 play important roles in the rapid induction of immediate-early genes in response to stress or mitogenic stimuli, either by inducing chromatin remodeling or by recruiting the transcription machinery. On the other hand, two other kinase targets, MAPKAPK2/MK2 and MAPKAPK3/MK3, participate in the control of gene expression mostly at the post-transcriptional level, by phosphorylating ZFP36 (tristetraprolin) and ELAVL1, and by regulating EEF2K, which is important for the elongation of mRNA during translation. MKNK1/MNK1 and MKNK2/MNK2, two other kinases activated by p38 MAPKs, regulate protein synthesis by phosphorylating the initiation factor EIF4E2. In the cytoplasm, the p38 MAPK pathway is an important regulator of protein turnover. For example, CFLAR is an inhibitor of TNF-induced apoptosis whose proteasome-mediated degradation is regulated by p38 MAPK phosphorylation. Ectodomain shedding of transmembrane proteins is regulated by p38 MAPKs as well. In response to inflammatory stimuli, p38 MAPKs phosphorylate the membrane-associated metalloprotease ADAM17. Such phosphorylation is required for ADAM17-mediated ectodomain shedding of TGF-alpha family ligands, which results in the activation of EGFR signaling and cell proliferation. Additional examples of p38 MAPK substrates are the FGFR1. FGFR1 can be translocated from the extracellular space into the cytosol and nucleus of target cells, and regulates processes such as rRNA synthesis and cell growth. FGFR1 translocation requires p38 MAPK activation. In the nucleus, many transcription factors are phosphorylated and activated by p38 MAPKs in response to different stimuli. The p38 MAPKs are emerging as important modulators of gene expression by regulating chromatin modifiers and remodelers. The promoters of several genes involved in the inflammatory response, such as IL6, IL8 and IL12B, display a p38 MAPK-dependent enrichment of histone H3 phosphorylation on 'Ser-10' (H3S10ph) in LPS-stimulated myeloid cells. This phosphorylation enhances the accessibility of the cryptic NF-kappa-B-binding sites marking promoters for increased NF-kappa-B recruitment. Phosphorylates NLRP1 downstream of MAP3K20/ZAK in response to UV-B irradiation and ribosome collisions, promoting activation of the NLRP1 inflammasome and pyroptosis. Phosphorylates methyltransferase DOT1L on 'Ser-834', 'Thr-900', 'Ser-902', 'Thr-984', 'Ser-1001', 'Ser-1009' and 'Ser-1104'.
Synonyms: p38b; SAPK2b; PRKM11; SAPK2; p38-2; p38Beta; P38BETA2
Tractability: Small molecule: an approved drug acts on it; a structure with a bound ligand is known; a high-quality ligand is known; it has a high-quality binding pocket; it belongs to a druggable protein family. PROTAC: it is named in the literature on targeted protein degradation; a small molecule that binds it is known.
Target class: Protein Kinase; CMGC protein kinase group; CMGC protein kinase p38 subfamily; CMGC protein kinase MAPK family; Enzyme; Kinase
Chemical probes: DORAMAPIMOD (high quality), PD082125, SR-302 (high quality), SR-318 (high quality)
Gene: Protein-coding gene on chromosome 22 (50,263,713 to 50,270,767, reverse strand). Ensembl gene ENSG00000185386.
Subcellular location: Cytoplasm; Nucleus
Subcellular location (Human Protein Atlas): Cytosol
Pathways (Reactome):
Signal Transduction: ERK/MAPK targets; RHO GTPases Activate NADPH Oxidases; VEGFA-VEGFR2 Pathway; p38MAPK events
Immune System: Activation of the AP-1 family of transcription factors; NOD1/2 Signaling Pathway; activated TAK1 mediates p38 MAPK activation
Cell Cycle: Ubiquitin-Mediated Degradation of Phosphorylated Cdc25A
Cellular responses to stimuli: Oxidative Stress Induced Senescence
Developmental Biology: Myogenesis
Metabolism of RNA: KSRP (KHSRP) binds and destabilizes mRNA
Organelle biogenesis and maintenance: Activation of PPARGC1A (PGC-1alpha) by phosphorylation
Gene Ontology:
Molecular function: MAP kinase activity; protein binding; protein serine kinase activity; protein serine/threonine kinase activity; ATP binding; protein kinase activity
Biological process: cellular response to interleukin-1; cellular response to UV-B; cellular response to virus; p38MAPK cascade; positive regulation of erythrocyte differentiation; positive regulation of gene expression; positive regulation of interleukin-12 production; stress-activated MAPK cascade; stress-activated protein kinase signaling cascade; cellular senescence; intracellular signal transduction; positive regulation of muscle cell differentiation; bone development; MAPK cascade; osteoblast differentiation
Cellular component: cytosol; nucleoplasm; cytoplasm; nucleus
Genetic constraint (gnomAD): Loss-of-function variants: 42 observed, 41.58 expected, observed/expected ratio (o/e) 1.01, 90% interval 0.79 to 1.31. The upper end of that interval is the gene's LOEUF score, 1.31, which puts it in group 5 of 6, group 1 being the genes least tolerant of losing a copy. Missense variants: 413 observed, 421.92 expected, observed/expected ratio (o/e) 0.98, 90% interval 0.9 to 1.06. Synonymous variants: 215 observed, 178.28 expected, observed/expected ratio (o/e) 1.21, 90% interval 1.08 to 1.35.
Homologues: Orthologues: chimpanzee MAPK11 (100% identical), macaque MAPK11 (99% identical), mouse Mapk11 (97% identical), rat Mapk11 (97% identical), guinea pig MAPK11 (88% identical), dog MAPK11 (83% identical), zebrafish mapk11 (82% identical), tropical clawed frog mapk11 (77% identical), pig MAPK11 (74% identical), Drosophila melanogaster p38a (63% identical), Caenorhabditis elegans pmk-1 (61% identical), Caenorhabditis elegans pmk-2 (56% identical), and 4 more. Paralogues in human: MAPK14 (73% identical), MAPK12 (62% identical), MAPK13 (59% identical), MAPK10 (48% identical), MAPK8 (48% identical), MAPK9 (48% identical), MAPK7 (44% identical), MAPK1 (43% identical), MAPK3 (43% identical), NLK (38% identical), MAPK15 (35% identical), MAPK6 (33% identical), and 7 more.